NKX1-1 (NK1 homeobox 1)
Description:
May be required for the coordinated crosstalk of factors involved in the maintenance of energy homeostasis, possibly by regulating the transcription of specific factors involved in energy balance.
Synonyms: SAX2; HSPX153; NKX-1.1
Tractability: No criterion of Open Targets' tractability assessment is met for any kind of drug.
Gene: Protein-coding gene on chromosome 4 (1,402,932 to 1,406,442, reverse strand). Ensembl gene ENSG00000235608.
Subcellular location: Nucleus
Subcellular location (Human Protein Atlas): Cytosol; Nucleoli fibrillar center
Gene Ontology:
Molecular function: DNA-binding transcription factor activity, RNA polymerase II-specific; RNA polymerase II cis-regulatory region sequence-specific DNA binding; DNA binding
Biological process: cell differentiation; regulation of transcription by RNA polymerase II; regulation of DNA-templated transcription
Cellular component: chromatin; nucleus
Homologues: Orthologues: macaque NKX1-1 (95% identical), chimpanzee NKX1-1 (90% identical), pig NKX1-1 (88% identical), dog NKX1-1 (81% identical), rat Nkx1-1 (76% identical), mouse Nkx1-1 (76% identical), guinea pig NKX1-1 (70% identical), tropical clawed frog nkx1-1 (45% identical), zebrafish nkx1.2lb (42% identical), Drosophila melanogaster NK7.1 (17% identical), Drosophila melanogaster HGTX (14% identical), Drosophila melanogaster scro (14% identical), and 4 more. Paralogues in human: NKX1-2 (31% identical), NKX6-1 (16% identical), NKX2-4 (15% identical), NKX3-2 (15% identical), NKX2-1 (15% identical), NKX2-3 (15% identical), NKX2-2 (15% identical), NKX2-6 (14% identical), NKX6-2 (13% identical), NKX2-5 (13% identical), NKX6-3 (13% identical), NKX2-8 (12% identical), and 1 more.
Diseases named in the same sentence as NKX1-1 in open-access papers:
NKX1-1 is named in the same sentence as 2 diseases in open-access papers, as found by Europe PMC text mining. Sharing a sentence is not in itself a finding about the gene and the disease. The quoted sentences say what the papers report.
bladder cancer (1 paper, 2023). "This test is based on the evaluation of three methylation biomarkers, TRNA-Cys, SIM2, and NKX1-1, and showed a sensitivity of 93.5% and a specificity of 92.6% in detecting bladder cancer." (PMID 37511475, 2023).
Insulin resistance (1 paper, 2011). Increased resistance towards insulin, that is, diminished effectiveness of insulin in reducing blood glucose levels. "NKX1-1(NK1 homeobox 1) may cause insulin resistance with a function in the maintenance of energy homeostasis." (PMID 21754918, 2011).